NOX1 (NADPH oxidase 1)
Diseases named in the same sentence as NOX1 in open-access papers (continued):
Sharing a sentence is not in itself a finding about the gene and the disease.
cancer (continued). "Recently, PEPCK-M up-regulation has been shown to promote metabolic adaptation to nutrient availability in cancer cells as a novel pro-survival mechanism and our results suggest an involvement of NOX1 in mediating this regulation." (PMID 25806803, 2015). "NOX1 expression was significantly higher in adenomatous polyp tissue compared to either normal or carcinoma." (PMID 25423035, 2014). "Carcinoma tissue NOX1 expression was variable with levels either similar to those of adenomatous polyp epithelium or markedly higher." (PMID 25423035, 2014). "To better understand how RV induces ROS generation in cancer cells, we investigated if RV treatment has any impact on the expression of Nox1, Nox2, Nox3, Nox4 and Nox5 in NSCLC cells." (PMID 23533664, 2013). "We demonstrate that NF-κB derived transcriptional up-regulation of Nox1 potentiates cancer cell adherence in response to an inflammatory stimulus." (PMID 23071493, 2012). "In conclusion, we have identified NOX1 as a novel mediator of angiogenesis and as a candidate therapeutic target for anti-angiogenic therapies in cancer." (PMID 21326871, 2011). "The aim of this review is to provide an overview on the role of Nox1 in cancer, as well as the contribution of our studies to demonstrate the involvement of Nox1 on neoplastic progression of human keratinocytes beyond the immortalization step." (PMID 20661536, 2010). "Besides, recent in vitro experiments have revealed that exosomal NADPH oxidase 1 (NOX1) promotes M2 polarization and mediates cancer development by stimulating reactive oxygen species (ROS) production in CC." (PMID 39165926, 2024). "The seven transmembrane NOXs, including dual oxidases 1 and 2 and NOX1-5, produce superoxide anion radicals and play various roles in pathophysiological disorders, including cardiovascular diseases, inflammation, neurodegeneration, and cancer." (PMID 39770941, 2024). "In addition, we demonstrate that NOX1, ADAM17, and membrane MCAM are present in a multiprotein complex in endothelial and cancer cells and that long-term treatment with NOX1 inhibitor partially decreases ADAM17 expression and the generation of sMCAM." (PMID 38137406, 2023). "On the contrary, an excessive expression of NOX1 may correlate with cancers of multiple epithelial tissues, acute lung inflammation and tissue fibrogenesis." (PMID 37134122, 2023). "ROS produced by NOX1 play a significant role in cancer development and metastasis." (PMID 37759771, 2023). "Additionally, we delve into the complex interplay of cellular components, including catalase and NOX1, in defending cancer cells against PDT-induced oxidative and nitrative stress." (PMID 38069213, 2023). "The potential of NOX1 as a ferroptosis-related predictor has been analyzed in many cancers." (PMID 35664309, 2022). "Many types of cultured cancer cell lines and human tumors at early and late stages of tumorigenesis express higher levels of NOX1, NOX2, NOX4, and NOX5 or their regulatory components compared with normal controls, suggesting a pivotal role either in cancer development or in progression." (PMID 34204425, 2021). "In colon, NOX1 may accelerate the adhesion of LPS-stimulated cancer cells through a mechanism in which TLR-4-mediated activation of NF-κβ leads to increased activation of NOX and a higher level of ROS, promoting the phosphorylation of Akt." (PMID 34205998, 2021).
cancer (continued). "Taken together, our data demonstrated that DDX19A could accelerate migration and invasion of CSCC cells in vitro and promote cancer cell metastasis in vivo via enhancing NOX1 expression." (PMID 33968728, 2021). "Evidence exists for TLR stimulation of NOX1 in cancer cells." (PMID 34205998, 2021). "Therefore, NOX1-driven invasion of cancer cells is based on the disruption of focal adhesions and increased expression of ECM-degrading enzymes, allowing cells to migrate locally and invade through ECM to initiate metastasis." (PMID 29478325, 2019). "Thus, it is likely that NOX1 is upregulated to promote cancer progression during stress situations, while NOX4 is a factor that produces ROS which contributes to cellular injury and senescence." (PMID 28423654, 2017). "However, NOX1 appears to be a general cancer promoting factor, especially in CRC while NOX4 by itself was not shown to promote CRC progression." (PMID 28423654, 2017). "In fact, we found to the contrary that both NOX1 and NOXA1 were significantly downregulated in B group cancers (NOX1, FC = –2.3, Jorissen cohort; NOXA1, FC = 1.3, both cohorts), which further supports the idea that exogenous, bacterially-derived ROS is a driver in B group CRCs." (PMID 27846243, 2016). "Although the pathway is typically up-regulated in cancer cells in order to support sustained energy production and biosynthesis, our results suggest that NOX1 acts to inhibit anaplerosis and redirect glutamate from the TCA cycle towards conversion to aspartate." (PMID 25806803, 2015). "Indeed aberrant gene transcription of some markers associated with carcinogenesis, NOX1, LGR5, MS4A12, reveal greatest deviation from that of normal tissue in the adenomatous polyps prior to development of carcinoma." (PMID 25423035, 2014). "To assess whether NOX1 may be a valuable target for cancer therapy, we used the inhibitor GKT136901." (PMID 21326871, 2011). "However, aberrant NOX1 activation and/or expression is involved in a growing number of diseases, including neurological disorders, atherosclerosis, hypertension, inflammation, and cancer, through the deregulation of cell metabolism." (PMID 36768405, 2023). "However, that report using non-human model cell lines contrasts with our finding that RAS mutation status is not significantly correlated with NOX1 mRNA expression in human transformed/cancer cells of the ATCC repository and the CCLE database." (PMID 32428030, 2020). "Notably, NF-κB activation is reportedly important for acquisition of stemness through dedifferentiation of intestinal epithelial cells, and the cooperation of the NF-κB and NOX1 signaling facilitate cell proliferation of both intestinal stem cells and cancer cells." (PMID 30700829, 2019). "However, there is a major difference between the experimental setting of these experiments: we acutely inhibited NOX1 function with a drug in established tumors, whereas the reported experiments were performed by injecting cancer cells with constitutively silenced NOX1 expression." (PMID 31249132, 2019). "However, it has been suggested that NADPH oxidase NOX1 plays a crucial role only in the initiation of tumorigenesis, as its expression is limited to the early stages of carcinogenesis and is downregulated in advanced cancers, excluding colon cancer." (PMID 29478325, 2019). "In addition to vascular cells, NOX1 is expressed various cells including neurons and cancer cells." (PMID 30889865, 2019). "These considerations add more levels of uncertainty in evaluating the possible role of GPX2 in cancer and general antioxidant function, particularly using cell lines, which by and large fail to replicate the high GPX2 and NOX1 levels of COAD/READ." (PMID 39329876, 2024).
cancer (continued). "We analyzed the association between clinical-pathological characteristics and the expression of NOX1, ADAM17, and MCAM mRNA in three datasets (GSE39582, The Cancer Genome Atlas, and PETACC3)." (PMID 38137406, 2023). "NADPH oxidase 1 (NOX1), derived reactive oxygen species and modulated by NOXA1, is crucial in the progression of cancer." (PMID 36925638, 2023). "The NADPH oxidase (NOX) family, which comprises seven members (NOX1–5, and DUOX1-2), is significant in the onset and development of cancer and has drawn growing attention as a significant source of ROS." (PMID 37626693, 2023). "Mitochondria and NOXs family, including NOX1, NOX2, NOX3, NOX4, NOX5, DUOX1, and DUOX2, are two important sources of ROS production in cancer cells." (PMID 35418176, 2022). "NOX1 is well recognized in its role in promoting angiogenesis, making the inhibition of both the NOX1 and NOX4 enzymes by GKT137831, an attractive therapeutic option for cancers." (PMID 35836253, 2022). "NOX1, an isoform of NOX, plays a well-known role in malignancy progression, angiogenesis, and signaling pathway in cancer development that has raised its significance in the NOX family." (PMID 32856850, 2020). "Mitochondria and NADPH oxidases of the Nox family including NOX1, NOX2, NOX3, NOX4, NOX5, DUOX1 and DUOX2, are two important sources of ROS production in cancer cells." (PMID 30755243, 2019). "The SRC proto-oncogene has been demonstrated to activate NADPH oxidases NOX1-, NOX3-, NOX4-, and NOX5-induced O2•− production in cancer models and to increase mutant SOD1 aggregate formation in ALS." (PMID 29478325, 2019). "Activation of NOX1 and generated superoxide and H2O2 serve as co-stimulatory signals for cell proliferation in many normal and cancer cells." (PMID 30889865, 2019). "The data demonstrate stable and low mRNA expression of NOX1, NOX3, NOX4, and NOX5, whereas the expression of NOX2 is markedly higher and variable in different forms of cancer." (PMID 29478325, 2019). "When using cancer cells with stable knockdown of PARP1, which form much smaller tumors, a significant rescuing effect by NOX1/4 depletion was detected." (PMID 29684820, 2018). "NADPH oxidase 1 belongs to a family of NADPH oxidase and cancer cells generally express more NOX isoforms." (PMID 29915721, 2018). "The NOX/DUOX family of NADPH oxidases consists of seven members (NOX1-5 and DUOX1-2), and it has received increasing attention for its correlation with cancer development and progression." (PMID 29296219, 2017). "In the transgenic adenocarcinoma of the mouse prostate (TRAMP) mice, NOX1 expression was significantly higher in high-grade prostatic intraepithelial neoplasia (PIN) and cancer cells, than in low-grade PIN and normal prostate epithelial cells." (PMID 29065504, 2017). "Two members of the annexin family (A2 and A3), both known to be over-expressed in many cancers including HCC, were reduced in NOX1 depleted HepG2 cells." (PMID 25806803, 2015). "NOS31 is highly selective and only affects cancer cells with high levels of NOX1, and neither interferes with XO nor acts as a scavenger of hydrogen peroxide." (PMID 38370049, 2024). "Further, three up-regulated genes, PRLR, NOX1, and PGF, also contributed to several hallmarks of cancer, mainly including insensitivity to antigrowth signals, self-sufficiency in growth signals, and evading apoptosis, indicating their potential roles in tumorigenesis." (PMID 35741849, 2022). "The NOXs inhibitor diphenyleneiodonium and the NOX1/4-specific inhibitor GKT137831 prevent erastin-induced ferroptosis in Calu-1 and HT1080 cells, suggesting that members of the NOX family promote ferroptosis of cancer cells." (PMID 36035208, 2022). "Therefore, NOX1 and COX2 (PTGS2) both play key roles in cancer development via the generation of an inflammatory microenvironment." (PMID 34073365, 2021).
cancer (continued). "However, in some cancer cell types, ADP-ribosylation emerged as an repressor of NOX1 and NOX4 since cell treatment with PJ34 resulted in upregulation of NOX1 and NOX4 mRNAs." (PMID 32900001, 2020). "Similarly, simultaneous depletion of NOX1 and NOX4 also reduced the ROS level in cancer cells treated with PJ-34." (PMID 29684820, 2018). "We demonstrated in this study that enhanced NOX1 and NOX4 expression and ROS production triggered by LTB4/BLT1 signal axis increases the pSmad3L, contributing to the resistance to the TGF-β1 growth-inhibitory effects in cancer cells." (PMID 26497676, 2015). "Therefore, we discuss the discuss the contribute of NOX1, NOX2, and NOX4 enzymes in the modulation of cellular metabolism and highlight their potential role for new therapeutic approaches that target the rewired metabolism of cancer cells." (PMID 36768405, 2023). "Levels of TFRC (P<0.001), PHKG2 (P=0.005), FADS2 (P<0.001), and NOX1 (P=0.011) mRNA relative expression were higher in cancer cells than in immune cells, whereas levels of ALOX5 (P<0.001) mRNA relative expression were lower in cancer cells than in immune cells." (PMID 35866375, 2022). "Moreover, the NOX1/4 inhibitor setanaxib (GKT137831) was shown to induce remarkable hypoxia-selective cytotoxicity in some HCC cell lines, thus representing a promising drug candidate for cancer therapy." (PMID 34204571, 2021). "However, the in vivoantitumor effect of GKT771 was not related to the presence or absence of NOX1 expression in cancer cells (i.e., DLD1 and LoVo cells)." (PMID 31249132, 2019). "However, owing to the nature of dual NOX1/NOX4 inhibition of GKT137831, NOX1 siRNA was also used to check the possibility of NOX1 involvement in TGF-β1 downregulation-induced ROS generation/ER stress and subsequent cancer cell death." (PMID 30523245, 2018). "p22phox is also the functional partner of other NOX isoforms such as NOX1, NOX3 and NOX4, and its lack of expression indicates that ATC cancer cells do not express these NADPH oxidase systems and consequently do not produce superoxide and H2O2 on their own." (PMID 21811634, 2011). "The increased TFRC, PHKG2, FADS2, NOX1, and reduced ALOX5 levels in LUSC tissues were reported in the present study, and scRNA-seq analysis showed that the levels of the five dysregulated genes were mainly influenced by cancer cells rather than immune cells." (PMID 35866375, 2022).
infection (28 papers, 2011 to 2025). The state of being infected such as from the introduction of a foreign agent such as serum, vaccine, antigenic substance or organism. "Nox1- and Nox2-deficient mice were also more susceptible to infection, indicating that this mechanism partially accounts for avirulence of type III strains in vivo." (PMID 30154263, 2018). "Rac1 and NAPDH oxidase (Nox1) are important contributors of ROS generation following infection and associated with gastrointestinal epithelial injury." (PMID 26761793, 2016). "Regardless of the exact mechanism of ROS production, the role of NADPH oxidase was also seen in vivo where both Nox1−/− and Nox2−/− mice showed increased infection of inflammatory macrophages during early infection with CTG, leading to increased susceptibility compared with wild-type mice." (PMID 30154263, 2018). "Nox1-deficiency provided a marked increase (3.7-fold) in survival following infection." (PMID 26910342, 2016). "On the other hand, Rac1 interacts with Nox1 and Nox2 in the signaling pathway to produce ROS required for infection-related development and pathogenicity in P. oryzae." (PMID 37108909, 2023). "On the other hand, NoxA (Nox1)– and NoxB (Nox2)–mediated fungal ROS production plays a crucial role in pathogen development and infection process." (PMID 36352882, 2022). "As a key member of the NOX family, NOX1 increases the release of ROS and facilitates ferroptosis, which further exacerbates plasmodium liver stage infection." (PMID 34369274, 2021). "To determine if the impact of NOX1−/− on LS parasites was hepatocyte-specific, we isolated primary hepatocytes from WT or NOX1−/− mice and infected primary hepatocyte cultures with P. yoelii sporozoites, and let infection proceed for 24 h." (PMID 31065106, 2020). "NOX1−/− mice exhibited a dramatic and statistically significant increase in LS burden when infection was assessed by PCR of P. yoelii 18s rRNA." (PMID 31065106, 2020). "In contrast, infection of TFR1 or NOX1 knockdown cell lines resulted in significantly increased numbers of LS parasites." (PMID 31065106, 2020). "Relative expression levels of nrf2, nox1, Mn-Sod, Cu/Zn-Sod, and cat genes in cod primary macrophages were down-regulated after infection with A. salmonicida." (PMID 31231379, 2019). "There was a significant increase of 3- to 7-fold in the percentage of CTG-infected Gr1+-F4/80+ cells in Nox1−/− and Nox2−/− mice compared to wild type, consistent with these mutants being less able to control early infection." (PMID 30154263, 2018). "O2•− production in BALF (bronchoalveolar wash fluid) cells of Nox1 knockout mice infected with IV subtype H3N2 is similar to that of wild-type littermates during the early stages of infection (day 3), but suppressed at late stages of infection (day 7)." (PMID 30049972, 2018). "Another counter-argument against is a difference in the kinetics of accumulation of NOX1 and NOX4 in HCV-infected cells: NOX1 is accumulated shortly after the infection, whereas a pronounced increase in the expression of NOX4 occurs only after two weeks." (PMID 27965466, 2017). "This interaction inhibits Rac1 activation and Nox1 expression, decreasing ROS generation that results from infection." (PMID 26761793, 2016). "This was confirmed by immunofluorescence staining that showed increased Nox1 after infection in APE1 suppressed cells compared to controls." (PMID 26761793, 2016). "It demonstrates for the first time a protective effect of Nox1 following infection by an external pathogen, in this case influenza viruses." (PMID 23577160, 2013). "We investigated the effect of Nox1−/y deficiency on the number and functionality of CD8+ and CD4+ T cells and of T regulatory cells at Day 7 post infection." (PMID 23577160, 2013).